LINC03143 (long independently transcribed non-coding RNA 3143)
Synonyms: U73166
Gene: Long non-coding RNA gene on chromosome 3 (50,260,249 to 50,263,358, forward strand). Ensembl gene ENSG00000230454.
Diseases named in the same sentence as LINC03143 in open-access papers:
LINC03143 is named in the same sentence as 1 disease in open-access papers, as found by Europe PMC text mining. Sharing a sentence is not in itself a finding about the gene and the disease.
LINC03143 shares sentences with these, for which no sentence is quoted: melanoma (1 paper).